MYSM1 (Myb like, SWIRM and MPN domains 1)
Description:
Metalloprotease with deubiquitinase activity that plays important regulator roles in hematopoietic stem cell function, blood cell production and immune response. Participates in the normal programming of B-cell responses to antigen after the maturation process (By similarity). Within the cytoplasm, plays critical roles in the repression of innate immunity and autoimmunity. Removes 'Lys-63'-linked polyubiquitins from TRAF3 and TRAF6 complexes (By similarity). Attenuates NOD2-mediated inflammation and tissue injury by promoting 'Lys-63'-linked deubiquitination of RIPK2 component (By similarity). Suppresses the CGAS-STING1 signaling pathway by cleaving STING1 'Lys-63'-linked ubiquitin chains. In the nucleus, acts as a hematopoietic transcription regulator derepressing a range of genes essential for normal stem cell differentiation including EBF1 and PAX5 in B-cells, ID2 in NK-cell progenitor or FLT3 in dendritic cell precursors. Deubiquitinates monoubiquitinated histone H2A, a specific tag for epigenetic transcriptional repression, leading to dissociation of histone H1 from the nucleosome.
Synonyms: 2A-DUB; KIAA1915; 2ADUB; BMFS4
Tractability: PROTAC: UniProt records ubiquitination sites on it; ubiquitination databases record sites on it.
Gene: Protein-coding gene on chromosome 1 (58,643,440 to 58,700,090, reverse strand). Ensembl gene ENSG00000162601.
Subcellular location: Nucleus; Cytoplasm
Subcellular location (Human Protein Atlas): Nucleoplasm; Nucleoli
Pathways (Reactome):
Metabolism of proteins: Metalloprotease DUBs
Gene Ontology:
Molecular function: histone binding; histone H2A deubiquitinase activity; metal-dependent deubiquitinase activity; protein binding; transcription coactivator activity; metallopeptidase activity; peptidase activity
Biological process: chromatin remodeling; positive regulation of transcription by RNA polymerase II; regulation of hemopoiesis
Cellular component: nucleolus; nucleoplasm; nucleus; protein-containing complex; cytoplasm
Genetic constraint (gnomAD): Loss-of-function variants: 30 observed, 70.43 expected, observed/expected ratio (o/e) 0.43, 90% interval 0.32 to 0.58. The upper end of that interval is the gene's LOEUF score, 0.58, which puts it in group 2 of 6, group 1 being the genes least tolerant of losing a copy. Missense variants: 659 observed, 725.48 expected, observed/expected ratio (o/e) 0.91, 90% interval 0.85 to 0.97. Synonymous variants: 235 observed, 237.41 expected, observed/expected ratio (o/e) 0.99, 90% interval 0.89 to 1.1.
Gene-disease validity (ClinGen):
ClinGen rates the evidence that MYSM1 causes each of these diseases.
bone marrow failure syndrome 4 (autosomal recessive): Definitive.
Homologues: Orthologues: chimpanzee MYSM1 (99% identical), macaque MYSM1 (97% identical), dog MYSM1 (88% identical), rabbit MYSM1 (86% identical), pig MYSM1 (84% identical), guinea pig MYSM1 (80% identical), mouse Mysm1 (79% identical), rat Mysm1 (77% identical), tropical clawed frog mysm1 (59% identical), zebrafish mysm1 (51% identical). Paralogues in human: SMARCC1 (17% identical), SMARCC2 (17% identical), MPND (15% identical).
Diseases named in the same sentence as MYSM1 in open-access papers:
MYSM1 is named in the same sentence as 95 diseases in open-access papers, as found by Europe PMC text mining. Sharing a sentence is not in itself a finding about the gene and the disease. The quoted sentences say what the papers report.
melanoma (10 papers, 2016 to 2025). A malignant, usually aggressive tumor composed of atypical, neoplastic melanocytes. "As a member of deubiquitinase family, MYSM1 has been reported to be associated with tumor progression in melanoma and colorectal cancer by only few studies with small sample sizes." (PMID 31761786, 2019). "Precisely, melanocyte specification in Mysm1-deficient mice was dysfunctional, and accordingly, MYSM1 knockdown in human melanoma cells resulted in reduced cell survival and proliferation." (PMID 28978033, 2017). "In the present investigation, we for the first time showed how phenotypical alterations in mice deficient in H2A deubiquitinase 2A-DUB/Mysm1 translate into functions of this enzyme in human tumor cells, using the example of melanoma." (PMID 28978033, 2017). "Originally, MYSM1 was discovered as a regulator of androgen receptor-dependent gene activation in prostate cancer, and more recently, has also been implicated in poor outcomes of colorectal cancer and in melanoma growth." (PMID 32466590, 2020). "Based on the identification of alterations in skin pigmentation and melanocyte specification in Mysm1-deficient mice, we hypothesized that MYSM1 may be involved in melanoma formation." (PMID 28978033, 2017). "Overall, our expression data from human and murine skin samples and human melanoma cell lines indicated that MYSM1 might be a gene associated with growth and survival of immature melanocyte precursors and melanoma cells that is inducible by UV and growth factor signals." (PMID 28978033, 2017). "The protein Myb‐Like SWIRM And MPN Domain‐Containing Protein 1 (MYSM1) is known to be responsible for deubiquitination of histone H2A but is shown to play an important role in malignant melanoma, too." (PMID 39212334, 2025). "For instance, elevated levels of the MYSM1 protein have been observed in human melanomas compared to normal melanocytes, and the knockdown of Mysm1 impairs the proliferation and survival of melanoma cell lines." (PMID 39684760, 2024). "MYSM1 expression is sensitive to chemotherapy-induced DNA damage response (etoposide) with nuclear recruitment to the γH2AX site in melanoma cells." (PMID 35884430, 2022). "In parallel IF analyses of cycling A375 melanoma cells, MYSM1 was found to redistribute to the nuclear periphery during M-phase of the cell cycle, and did not colocalize with either Ki-67 or condensed HH3." (PMID 32466590, 2020). "Like 2A-DUB/MYSM1, the newly-identified MYSM1 interaction partners, HELLS and RFC4/5, have also been implicated in tumorigenesis, specifically in melanoma growth; HELLS is frequently misregulated in a variety of cancers." (PMID 32466590, 2020). "In A375 melanoma cells that appeared highly sensitive to etoposide, similar increases in MYSM1 and γH2AX were found." (PMID 32466590, 2020). "Upon stable silencing of MYSM1 in A375 and SK-MEL-28 melanoma cells by lentivirally-mediated shRNA expression, survival and proliferation were significantly reduced in five MYSM1 shRNA cell lines analyzed compared with control cells." (PMID 28978033, 2017). "Expression of MYSM1 in melanocytic nevi was less consistent and at an intermediate level compared with normal melanocytes and melanoma." (PMID 28978033, 2017). "Firstly, our data indicate that MYSM1 participates in the regulation of genes involved in melanoma survival and proliferation, such as c-MET, via functional interaction with the sequence-specific TF PAX3." (PMID 28978033, 2017). "Quantification of MYSM1+Melan-A+ double-positive cells in normal skin, melanocytic nevi, and melanoma confirmed the increase in MYSM1 expression during step-wise transformation of normal melanocytes to malignant melanoma cells." (PMID 28978033, 2017). "In melanoma skin metastases, MYSM1 expression was consistently detectable in the majority of tumor cell nuclei as confirmed by double-staining for MYSM1 and Melan-A." (PMID 28978033, 2017).
melanoma (continued). "In context with our finding that MYSM1 bound to the c-MET promoter region in close vicinity to PAX3 in melanoma cells, our data indicate that MYSM1 is an epigenetic regulator of melanoma growth and potentially promising new target for tumor therapy." (PMID 28978033, 2017). "In this investigation, we therefore analyzed the function of MYSM1 in melanocytes and melanoma cells using mouse models, patient material, and tumor cell lines." (PMID 28978033, 2017). "MYSM1 as a histone H2A deubiquitinase has been reported to activate the transcription of its downstream genes, including CDH1, c-MET, or genes encoding ribosomal proteins via histone H2A deubiquitination in colorectal cancer, melanoma, and B cell lymphoma." (PMID 38177530, 2024). "An MYSM1 protein quantification showed an incremental increase during the progressive transformation of normal melanocytes into malignant melanoma cells with a correlation with c-KIT expression in melanoma." (PMID 35884430, 2022). "Furthermore, elevated MYSM1 protein levels were observed in human melanomas compared to normal melanocytes, and Mysm1-knockdown impaired the proliferation and survival of melanoma cell lines." (PMID 32344625, 2020). "Few studies found that MYSM1 was involved in melanoma growth and colorectal cancer metastasis." (PMID 31761786, 2019). "Corresponding Western Blot analyses performed with A375 melanoma cells revealed that MYSM1 protein expression was regulated by growth factor signals as indicated by down-regulation of MYSM1 upon serum-starvation in context with inhibition of MEK- and Akt-signaling." (PMID 28978033, 2017). "Given the potential function of Mysm1 in DNA-damage response (DDR) pathways and the critical role of UV light in melanoma cell formation and cellular transformation, we subsequently investigated if Mysm1 was inducible in murine skin upon irradiation with UVB using established protocols." (PMID 28978033, 2017). "However, significant amounts of MYSM1 were detectable in the nuclei of Melan-A-positive melanoma cells in all 10 human superficial spreading melanoma (SSM) samples tested (third panel, representative sample)." (PMID 28978033, 2017). "Accordingly, MYSM1 may co-operate with TF important for melanoma transformation to promote survival and growth of these tumor cells." (PMID 28978033, 2017). "Studies have shown that MYSM1 expression exhibits distinct pattern in different cancers: it is notably reduced in certain colorectal cancer tissues compared to in normal tissues, while showing significant elevation in some melanoma tissues relative to the surrounding tissues." (PMID 39684760, 2024). "In a separate study, Mysm1-/- macrophages were confirmed to have elevated production of pro-inflammatory cytokines in response to stimulation, as well as increased proliferation, increased apoptosis, and enhanced capacity to control melanoma tumor growth in vivo in mouse models." (PMID 32344625, 2020). "In order to validate the concept of MYSM1 upregulation in primary and metastatic melanoma in a larger number of melanoma patients, we subsequently evaluated MYSM1 expression in a melanoma tissue microarray containing 62 malignant melanoma samples, 20 metastatic melanoma, and 18 nevus tissues." (PMID 28978033, 2017). "In addition, we explored how MYSM1 as histone-modifying enzyme may regulate tumor genes in melanoma." (PMID 28978033, 2017). "In addition, in a subfraction of primary and metastatic melanomas, co-expression of MYSM1 with c-MET could be verified." (PMID 28978033, 2017).
melanoma (continued). "In addition, MYSM1-silenced melanoma cells proliferated less well in softagar assays." (PMID 28978033, 2017). "Similarly, MYSM1 was found at increased levels in c-KIT-positive melanoma." (PMID 28978033, 2017). "Wilms and team revealed that MYSM1 is involved in the regulation of survival‐ or proliferation‐relevant genes, like c‐MET, leading to the progression of malignant melanoma." (PMID 39212334, 2025). "In line with a function of MYSM1 in the regulation of c-MET in melanoma cells, c-MET mRNA expression was significantly decreased in A375 cells lentivirally silenced for MYSM1 in comparison with scrambled control A375 cells." (PMID 28978033, 2017). "In line with high expression in SSM and melanoma metastasis in situ, human melanoma cell lines A375 and SK-MEL-28 were strongly positive for MYSM1 that mainly localized to the nuclei." (PMID 28978033, 2017). "Subsequently, to test the influence of MYSM1 knockdown on anchorage-independent growth of A375 and SK-MEL-28 melanoma cells, softagar assays were performed." (PMID 28978033, 2017). "Upon MYSM1 knockdown, reduced overall proliferation and viability of A375 and SK-MEL-28 melanoma cells was measured by trypan blue exclusion and cell counting (not shown)." (PMID 28978033, 2017). "Melanoma clones lacking MYSM1 have been found to exhibit reduced overall proliferation and viability, including in 3D culture models, with increased apoptosis." (PMID 35884430, 2022). "In initial protein expression and localization analyses, significant amounts of MYSM1 were detectable in a variety of human cell types, including PBMC, KG-1a myeloid leukemia cells, A375 and SK-MEL-28 melanoma cells, HepG2 liver cancer cells, and A172 glioblastoma cells, mainly in the nuclei." (PMID 32466590, 2020). "In human melanoma samples, expression of MYSM1 was increased compared with normal skin melanocytes and nevi and co-localized with melanocyte markers such as Melan-A and c-KIT." (PMID 28978033, 2017). "Moreover, in accord with the function of MYSM1 as H2A deubiquitinase, overall H2A-K119ubi was increased in the nuclei upon knockdown of MYSM1 in A375 and SK-MEL-28 melanoma cells." (PMID 28978033, 2017). "Moreover, MYSM1 was highly expressed and co-localized with PAX3 and c-MET in melanoma cells in culture and in SSM samples in situ." (PMID 28978033, 2017). "In addition, co-localization of MYSM1 and PAX3 could be detected in the nuclei of exponentially growing A375 melanoma cells by IF staining – underpinning that these two transcriptional regulators co-operate in gene regulation in melanoma." (PMID 28978033, 2017). "Additionally, MYSM1 expression has been identified in various tumor cells, including castration-resistant prostate cancer (CRPC) cells, colorectal cancer (CRC) cells, melanoma cells, ERα-positive breast cancer (BC) cells, and triple-negative breast cancer (TNBC) cells." (PMID 39684760, 2024). "Furthermore, we found that the thymocytes from B16 melanoma-bearing mice, which display severe thymus atrophy at late tumor stages, exhibited reduced Mysm1 and IRF2 expression but enhanced Sca1 expression, suggesting that tumors may downregulate Mysm1 and IRF2 for thymic T-cell elimination." (PMID 27277682, 2016).
prostate carcinoma (9 papers, 2017 to 2024). A carcinoma that arises from epithelial cells of the prostate gland. "MYSM1 co-activates androgen receptor (AR) action to promote prostate cancer, while MYSM1 inhibits castration-resistant prostate cancer (CRPC) process through PI3K/Akt signaling regulation." (PMID 38177530, 2024). "Monoubiquitinated histone H2A-K119ub was the first MYSM1 substrate to be discovered, and MYSM1 was shown to promote the expression of androgen receptor target genes in prostate cancer cell lines through H2A-K119ub deubiquitination." (PMID 36611064, 2023). "We and other groups also revealed an antitumor effect of MYSM1 in prostate cancer and renal carcinoma." (PMID 34706761, 2021). "MYSM1 was originally characterized as an epigenetic regulator that promotes the expression of androgen receptor target genes in prostate cancer cell lines, through deubiquitination of histone H2AK119ub." (PMID 32344625, 2020). "Here, we investigated the role of histone deubiquitinase MYSM1 in the pathogenesis of prostate cancer (PCa)." (PMID 31761786, 2019). "To further verify the expression of MYSM1 in prostate cancer, we analyzed 2 microarray datasets (Grasso Prostate and Taylor Prostate 3) from Oncomine database." (PMID 31761786, 2019). "Immunostaining analyses revealed that MYSM1 protein levels were a little lower in prostate cancers when compared with benign prostatic hyperplasia." (PMID 31761786, 2019). "Thus, MYSM1 was originally characterized as a positive regulator of androgen receptor target gene expression in human prostate cancer cell lines." (PMID 32344625, 2020). "In addition, the expression of MYSM1 inversely correlates with Gleason grade, Gleason score and recurrence status, establishing MYSM1 as a cancer-related marker in prostate cancer." (PMID 31761786, 2019). "In support of this concept, 2A-DUB/MYSM1 was originally discovered as regulator of androgen receptor-dependent gene expression in a co-regulatory complex with histone acetylase p/CAF in prostate cancer cells that displayed reduced overall levels of H2A-K119ubi compared with normal prostate tissue." (PMID 28978033, 2017). "MYSM1 is required for the activation of several target genes in prostate cancer cells and the levels of monoubiquitinylated H2A are dramatically decreased in prostate tumors, suggesting MYSM1 expression may be involved in tumor biological functions." (PMID 28498834, 2017). "Moreover, levels of monoubiquitinylated H2A are dramatically decreased in prostate tumors and MYSM1 is required for the activation of several target genes in prostate cancer cells, suggesting MYSM1 expression may serve as a cancer marker." (PMID 28498834, 2017). "In fact, previous studies have demonstrated that MYSM1 interplays with p/CAF to form a co-regulatory protein complex that stepwise synergizes histone ubiquitination and acetylation for AR-dependent gene activation in prostate cancer cells." (PMID 38177530, 2024).